TNF (tumor necrosis factor)
Diseases named in the same sentence as TNF in open-access papers (continued):
Sharing a sentence is not in itself a finding about the gene and the disease.
coronary artery disease (continued). "However, there are few studies on the expression of serum SAH, IL-1β, Hcy, TNF-α, and BDNF in coronary heart disease and their relationship with the extent of coronary artery stenosis." (PMID 35282820, 2022). "miR-146a expression levels were negatively correlated with TNF-α levels, irrespective of other metabolic or inflammatory parameters, and with the severity of coronary artery disease." (PMID 34199767, 2021). "Inflammation is a key player in the development and progression of coronary heart disease (CHD) and testosterone has been shown to dampen the inflammatory response by suppressing the expression of TNF-α and IL-1β in stimulated human macrophages cultured in vitro." (PMID 32714315, 2020). "For example, tissue ECE activity is correlated with coronary artery disease, while ECE-1 activity was show to be upregulated during buccal mucosal ulcer and gastric ulcer in rats and accompanied by the induction of TNF-α and apoptosis." (PMID 31231580, 2019). "In case of suffering from coronary artery disease (CAD), the epicardial adipose tissue displayed significantly higher levels of chemokine (MCP-1) and several inflammatory cytokines (IL-1β, IL-6, IL-6sR, and TNF-α), comparing to subcutaneous adipose tissue." (PMID 28757877, 2017). "It has been shown that EAT produces inflammatory mediators such as interleukin (IL)-6, IL-1b, tumor necrosis factor (TNF)-a, and monocyte chemotactic protein (MCP-1) in patients with significant coronary artery disease and expresses mRNAs of adiponectin, resistin, leptin, IL-6, TNF-a, and CD-45." (PMID 23762053, 2013). "Several cytokines including TNF-α, TGF-β, and different interleukins (ILs) such as IL-1, IL-4, IL-6, IL-8, and IL-18 are involved in the development of various inflammatory cardiac pathologies, namely, ischemic heart disease, myocardial infarction, heart failure, and cardiomyopathies." (PMID 41311551, 2025). "In patients with coronary artery disease, the local expression of chemokine (monocyte chemotactic protein 1 (MCP1)) and inflammatory cytokines (IL-1β, IL-6, and TNF-α) was observed with significant changes in MCP1, IL-1β, IL-6, TNF-α mRNA, and protein in the epicardial adipose stores." (PMID 36768479, 2023). "Therefore, this reflects again that TNF and its co-regulatory genes like TRAF5 might play a crucial role in coronary artery disease." (PMID 27171184, 2016). "In this regard, it is pointed out that in patients with coronary artery disease-related CHF but not with idiopathic dilated cardiomyopathy-related CHF, TNFα levels were elevated in the plasma along with an atherogenic lipid profile." (PMID 38256155, 2024). "Conclusions: miR-146a expression levels were negatively correlated with TNF-α levels in patients with SCAD, irrespective of other metabolic or inflammatory markers, and with the severity of coronary artery disease." (PMID 34199767, 2021).
leukemia (279 papers, 1994 to 2026). A malignant (clonal) hematologic disorder, involving hematopoietic stem cells and characterized by the presence of primitive or atypical myeloid or lymphoid cells in the bone marrow and the blood. "A possible risk in regard to the development of lymphomas, leukemia, or other hematopoietic or solid malignancies, in patients treated with a TNF antagonist cannot be excluded." (PMID 40095618, 2025). "It has been reported that the reduction in serum levels of tumor necrosis factor alpha (TNF-α) following systemic chemotherapy in lymphoproliferative malignancies (leukemia and lymphoma) in patients is linked with response rates." (PMID 41516140, 2025). "Studies indicate that infliximab, a TNFα blocker, can increase the risk of leukemia and lymphoma, possibly by reducing T-cell recognition of cancer cells and increasing the risk of tumor cell proliferation and metastasis." (PMID 38886470, 2024). "A clinically study indicated that poor TKI responders had an enrichment of genes associated with the TGF-β and TNF-α pathways and a quiescence signature that maintains leukemia-initiating cells in chronic myeloid leukemia." (PMID 38927668, 2024). "Elevated levels of pro-inflammatory cytokines such as tumor necrosis factor-alpha (TNF-α) have been associated with poor outcomes in leukemia." (PMID 39658797, 2024). "In hepatic LAMs, the majority of M1-associated genes, including CCL5, CXCL1, IL-12β, iNOS, and TNF-α, exhibit increased expression during leukemia progression." (PMID 38779660, 2024). "The TNF-α rs1800629 polymorphism has been associated with higher cytokine production and increased leukemia risk." (PMID 39658797, 2024). "Polymorphisms in the TNF-α promoter have been described in leukemia, as the frequency of TNF-α-308 G/A polymorphism in ALL and CLL cases is associated with a higher risk of death." (PMID 35897788, 2022). "Studies have also shown that celastrol inhibited TNF-mediated NF-κB signaling pathway to promote TRAF2 associated apoptosis in leukemia cells." (PMID 29190976, 2017). "In an AML mouse model, leukemia-initiating cells (LICs) or leukemia stem cells (LSCs) exhibit autocrine TNF-α secretion, which causes constitutive activation of NFκB activity in this unique cell population." (PMID 25823927, 2015). "This study was the second in challenging the -1082 (IL10 gene) and -308 (TNF alpha gene) polymorphisms, together, in leukemia." (PMID 23213548, 2012). "Interestingly, elevated levels of TNF-α were associated with leukemia progression and extramedullary infiltration in AML and ALL." (PMID 41129238, 2026). "Although we did not directly investigate the upstream mechanisms regulating CXCL10 induction in this study, our findings of reduced IFN-γ, TNF-α, and IL-27 expression in leukemia-bearing CXCL10-deficient mice underscore the need for further mechanistic studies." (PMID 41129238, 2026). "Moreover, RA treatments such as methotrexate (MTX), Janus kinase (JAK) inhibitors, and anti-TNF therapies have complex implications, with some studies suggesting potential contributions to leukemia risk through immune suppression and hematopoietic alterations." (PMID 41141147, 2025). "This sets up a vicious cycle in which the poor negative response inhibition of the JAK2 mutation clone by inflammatory cytokine TNF-α produces more ROS, inducing more genetic alteration changes that eventually lead to the development of myelofibrosis or leukemia, as proposed by Hasselbalch." (PMID 39157201, 2024). "Interestingly, higher levels of TNFα expression are frequently linked to unfavorable clinical characteristics and refractory disease in leukemia." (PMID 37371757, 2023). "In addition to its role in influencing a tumor microenvironment in the case of solid malignancies, TNF- α has been found to be associated with adverse clinical manifestations of leukemia including extramedullary infiltration and resistance to chemotherapy." (PMID 37232720, 2023).
leukemia (continued). "Furthermore, it has been demonstrated earlier that in human leukemia U937 cells, RA caused cell death by down-regulating TNF-α-regulated NF-κB activation and ROS generation." (PMID 35079027, 2022). "In addition to being produced by a wide variety of malignant cells and immune cells within the tumor-associated microenvironment, TNF-α can be produced by leukemia cells." (PMID 35897788, 2022). "Taken altogether, these results support a role of miR-126 in determining enrichment of the Sca-1high EC fraction and in turn arteriolar density in the BM niche and a role of TNFα-dependent miR-126 downregulation in the loss of arterioles during leukemia growth." (PMID 34372909, 2021). "Indeed, the TNFα promoter has a variety of polymorphisms that have been linked to leukemia." (PMID 37371757, 2023). "Researchers investigating how to treat leukemia, discovered that depleting macrophages, can induce cellular death in leukemia via the TNF pathway and alter the tumor microenvironment for an anti-tumor effect." (PMID 41041337, 2025). "Elevated levels of pro-inflammatory cytokines, particularly tumor necrosis factor-alpha (TNF-α), interleukin-6 (IL-6), and interleukin-17 (IL-17), are fundamental to both RA and leukemia progression." (PMID 41141147, 2025). "Leukemia-specific cells are specifically triggered immune cells that produce interferon gamma (IFNg), tumor necrosis factor α (TNFα) or initiate cells’ degranulation in the presence of leukemia-associated antigens (LAA) like WT1 or PRAME." (PMID 41226377, 2025). "The extract leads to a decrease in TNF-α on benzene-induced leukemia in Wistar rats, demonstrating its promising immunotherapy for leukemia." (PMID 41516140, 2025). "Alternatively, leukemia-derived DCs, i.e., leukemia cells differentiated in vitro toward a DC-like phenotype with GM-CSF, IL-4, TNF-α, and CD40L, are used." (PMID 41463107, 2025). "In cancer or leukemia settings, the addition of TNF-α, IL-6, IFN-γ, and TLR agonists (e.g., LPS or poly I:C) increases cell immunogenicity and supports the maturation of the DC phenotype." (PMID 41463107, 2025). "We found that CD8 KO had a minimal effect on responses to cytokines or HL60 cells, but led to modestly higher degranulation (CD107a) and TNF production against K562 leukemia cells." (PMID 38805302, 2024). "A study showed that the inhibition of TNF-α enhanced NF-κB inhibition-induced apoptosis in leukemia cells while protecting healthy hematopoietic and other tissue cells." (PMID 39315246, 2024). "As a precursor of the auxin, tryptophol not only possesses hypnotic effect and reduces the production of Prostaglandin E2 (PGE2), TNFα, and IFNγ, but also inhibits the activity of butyrylcholinesterase and the proliferation of leukemia U937 cells." (PMID 38396889, 2024). "The results demonstrated that pretreatment with OFI-EVs decreased the activity and gene expression of pro-inflammatory cytokines (IL-6, IL-8, and TNF-α) in the LPS-stimulated human leukemia monocytic cell line (THP-1)." (PMID 39000212, 2024). "Dihydroquercetin 4′-methyl ether, from B. balsamifera was found to overcome tumor necrosis factor (TNF)-related apoptosis-inducing ligand (TRAIL) resistance in leukemia cells." (PMID 38731504, 2024). "It has been reported that TNF-α is highly expressed in leukemia stem cells (LSC), and its abundant expression is closely associated with poor clinical indicators." (PMID 38671491, 2024). "We then attempted to achieve a preliminary exploration of the pathogenesis of leukemia through the study of five prognostic genes (TNF, CXCR3, CD4, PIK3CA and CALR)." (PMID 38671491, 2024). "TNF-α induces NF-κB-dependent and NF-κB-independent survival signaling, hence promoting proliferation of leukemia cells." (PMID 39315246, 2024). "DHEAS can influence the inflammatory response by modulating the production of inflammatory factors such as TNF-α and IL-6, thereby impacting the progression of leukemia." (PMID 39351228, 2024).
leukemia (continued). "In another study, CANA decreased the levels of TNFα, IL-1α, IL-6 and reactive oxygen species (ROS) in LPS-stimulated RAW264.7 macrophages, as well as TNFα and IL-1β in LPS-treated human leukemia monocytic cells (THP-1)." (PMID 37086302, 2024). "The anti-inflammatory effects of mesalazine on the release of interleukin (IL)-6 and tumour necrosis factor alpha (TNF-α) were analysed using human leukemia monocytic cell line (THP-1)." (PMID 38474043, 2024). "Blockade of TNF using an anti-TNF antibody massively shortened the survival in the L1210 and P815 mouse leukemia models, demonstrating that TNF plays a critical role in this setting." (PMID 38500877, 2024). "In vitro studies have shown that knockout of TNF-α (+) expression can make leukemia cells more sensitive to chemotherapy and delay leukemia relapse (in mouse models)." (PMID 38671491, 2024). "The human PLB-985 leukemia cell line can be differentiated in vitro into neutrophil-like cells, which produce reactive oxygen species (ROS) in response to TNFα." (PMID 36986875, 2023). "We also observed a strong correlation between the TNF-α rs1800629 AA and TNF-α-(GA+GG) genotypes with leukemia susceptibility in the recessive inheritance model." (PMID 37232720, 2023). "Rh2 also inhibits cell growth and induces apoptosis of human leukemia (HL-60) cells via the tumor necrosis factor-α (TNF-α) pathway." (PMID 36771109, 2023). "Gene concentration analysis (GSEA) revealed that genes related to leukemia apoptosis and tumor necrosis factor were more abundant in LDB1 knockdown cells than in the control cells." (PMID 37573405, 2023). "A previous study on polymorphic variation of TNF–α rs1800629 (–308 G>A) in leukemia demonstrated that the frequency of the rs1800629 GA genotype was high in the patient group as compared to healthy controls and it was associated with high risk of adult B-ALL." (PMID 37232720, 2023). "We analyzed the expression of receptors for IFN-γ and TNF-α on the surface of leukemia cells by quantifying the antigen binding capacity for TNF-α receptor type 1 (TNFR-1), TNF-α receptor type 2 (TNFR-2), IFN-γ receptor (INFGR) and membrane bound TNF-α." (PMID 37610672, 2023). "Acute myelogenous, acute lymphoblastic, chronic myelogenous, chronic lymphocytic, and hairy cell leukemia cells are examples of leukemia cells that produce TNFα." (PMID 37371757, 2023). "In vitro studies targeting the T-cell leukemia cell line HSB2 showed that CD26-2G/3G exhibited significant anti-leukemia effects with the secretion of granzymeB, TNFα, and IL-8, with 3G being superior to 2G." (PMID 37626869, 2023). "The versatile results of this study are promising and in accordance to earlier findings, proving that curcumin as another turmeric compound suppressed TNF-related NF-κB activation as well as proliferation in leukemia cells." (PMID 36185259, 2022). "An in vitro study also demonstrated that adlay bran extract reduced the excretion of TNFα and IL-6 in basophilic leukemia cells, which is consistent with our results." (PMID 35684050, 2022). "Previous studies have shown that AML leukemia cells can produce endogenous TNFα, which then activated the downstream NFκB-signaling pathway, thereby resulting in leukemia cell proliferation and drug resistance." (PMID 35938037, 2022). "Since TNFα is one of the NF-κB target genes, leukemia progression is maintained by the NF-κB/TNFα feedback loop." (PMID 35884618, 2022). "Abnormal cytokine signaling pathways are characteristic of all types of leukemia, especially IL-1, TNF-α, and IL-6, which are considered key cytokines that disrupt hematopoietic cell function and promote the development of inflammation." (PMID 35441668, 2022). "TNF-α promotes leukemia cell survival and development by activating the nuclear factor kappa B (NF-KB) and c-Jun N-terminal kinase/activator protein-1 (JNK/AP-1) pathways, which inhibit apoptosis and promote proliferation." (PMID 35547942, 2022).
leukemia (continued). "High concentrations of TNF-α have been reported to be involved in leukemogenesis, the tumor microenvironment, leukemia cell proliferation, and chemoresistance." (PMID 35806401, 2022). "Given that SEM-Mb does not contain a heme group, we believe that the mechanism by which SEM-Mb induces TNF-α upregulation in leukemia cells differs from that of heme in macrophages." (PMID 36145287, 2022). "IL-10 and TNF concentrations were significantly higher in the post-index group compared to the pre-index group among head and neck carcinoma and leukemia patients, respectively." (PMID 35476641, 2022). "Conversely, NF-κB inhibition in LICs curbs tumorigenesis in vivo, suggesting that the NF-κB/TNFα axis supports leukemia progression." (PMID 35884618, 2022). "In the post-index group, the concentration of IL-1β and TNF in head and neck carcinoma were significantly higher than those in leukemia (p < 0.01 and p < 0.01, respectively)." (PMID 35476641, 2022). "A pathway regulating p38 MAPK-mediated TNF-α expression also explains the cytotoxicity of SEM-Mb in the human leukemia cell lines HL-60, THP-1, K562, Jurkat, and ABT-199-resistant U937." (PMID 36145287, 2022). "The in vitro investigation of the anti-inflammatory properties of several Scorzonera species present in Turkey revealed that aqueous methanolic extracts from the aerial parts of the plants can inhibit TNF-α production in LPS-treated leukemia cells." (PMID 36232888, 2022). "Improved leukemia control is likely due to the ability of this population of CAR T cells to continuously produce TNFα and maintain phosphorylation of key intracellular molecules imperative for T cell activation and function." (PMID 34750374, 2021). "In further work from this laboratory, it was shown that by activating the EC using TNF-α it was possible to monitor the interaction of EC with leukemia cells HL-60 and KG-1 by measuring the changes in resonant frequency and dissipation." (PMID 34073054, 2021). "But how do the TNFα-induced vascular changes in the leukemic BM niche ultimately promote leukemia growth?" (PMID 34372909, 2021). "For example, Rg1 inhibits TNF-α expression in THP-1 human leukemia cells, whereas the ginsenoside Rh1 increases TNF-α expression." (PMID 35003268, 2021). "In these cases, it is likely that inhibition of TNF-α in combination with modulation of other cytokines is needed for the eradication of the leukemia-initiating cells." (PMID 34804065, 2021). "It is clear that the combined increased gene expression of IL-1β, the secretion of IL-10, GM-CSF, and TNFα, and decreased secretion of IL-8 contribute to the anti-proliferative effects of carnosine on U937 promonocytic leukemia cells." (PMID 33809496, 2021). "TNF was, among others, suggested to form a positive feedback loop with NF-κB resulting in enhanced leukemia progression, and high TNF serum levels correlate with poor event-free and overall survival of AML patients." (PMID 34885231, 2021). "Tumor necrosis factor (TNF)-related apoptosis-inducing ligand (TRAIL) transduced leukemia cells can produce TRAIL+ secreted exosomes." (PMID 34239869, 2021). "AML blasts express high levels of TNFα, and likely hijack TNFα-driven mechanisms of normal hematopoiesis to support leukemia growth." (PMID 34372909, 2021). "In leukemia, TNF-α contributes to tumorigenesis and activates the suppressive functions of Treg cells." (PMID 32346605, 2020). "These improve the tumor’s ability to evade the immune system, indicating a way to use anti-TNF therapy in leukemia." (PMID 32346605, 2020). "Surprisingly, we observed the same molecular sequence; TNF-α and IL-6 were simultaneously secreted in leukemia cells and in PBMCs following treatment with free DOX or the conjugate." (PMID 33321722, 2020). "Khwaja and colleagues reported that inhibition of the FADD/caspase signaling pathway sensitizes leukemia cells to TNFα-induced cell death." (PMID 32194778, 2020).